DEGS1 (delta 4-desaturase, sphingolipid 1)
Description:
Has sphingolipid-delta-4-desaturase activity. Converts D-erythro-sphinganine to D-erythro-sphingosine (E-sphing-4-enine). Catalyzes the equilibrium isomerization of retinols (By similarity).
Synonyms: DES1; MLD; MIG15; Des-1; FADS7; DEGS-1; DEGS; HLD18
Tractability: Antibody: its Gene Ontology location is reachable by antibodies, with high confidence; UniProt predicts a signal peptide or a membrane-spanning region. PROTAC: ubiquitination databases record sites on it; a small molecule that binds it is known.
Target class: Enzyme; Oxidoreductase
Gene: Protein-coding gene on chromosome 1 (224,175,756 to 224,193,441, forward strand). Ensembl gene ENSG00000143753.
Subcellular location: Mitochondrion membrane; Endoplasmic reticulum membrane
Subcellular location (Human Protein Atlas): Mitochondria; Cytokinetic bridge; Plasma membrane; Primary cilium
Pathways (Reactome):
Immune System: Neutrophil degranulation
Metabolism: Sphingolipid de novo biosynthesis
Gene Ontology:
Molecular function: protein binding; retinol isomerase activity; sphingolipid delta-4 desaturase activity; electron transfer activity; catalytic activity
Biological process: ceramide biosynthetic process; glycosphingolipid biosynthetic process; myelin maintenance; sphingomyelin biosynthetic process; sphingolipid biosynthetic process; unsaturated fatty acid biosynthetic process; lipid metabolic process
Cellular component: cytoplasmic side of endoplasmic reticulum membrane; endoplasmic reticulum membrane; mitochondrial membrane; mitochondrion; endoplasmic reticulum; membrane; plasma membrane; specific granule membrane
Genetic constraint (gnomAD): Loss-of-function variants: 18 observed, 25.4 expected, observed/expected ratio (o/e) 0.71, 90% interval 0.49 to 1.05. The upper end of that interval is the gene's LOEUF score, 1.05, which puts it in group 4 of 6, group 1 being the genes least tolerant of losing a copy. Missense variants: 366 observed, 410.07 expected, observed/expected ratio (o/e) 0.89, 90% interval 0.82 to 0.97. Synonymous variants: 134 observed, 137.92 expected, observed/expected ratio (o/e) 0.97, 90% interval 0.84 to 1.12.
Gene-disease validity (ClinGen):
ClinGen rates the evidence that DEGS1 causes each of these diseases.
leukodystrophy, hypomyelinating, 18 (autosomal recessive): Definitive.
Homologues: Orthologues: chimpanzee DEGS1 (99% identical), macaque DEGS1 (98% identical), dog DEGS1 (90% identical), pig DEGS1 (89% identical), guinea pig DEGS1 (88% identical), mouse Degs1 (85% identical), rat Degs1 (85% identical), tropical clawed frog degs1 (81% identical), rat Degs1l2 (75% identical), zebrafish degs1 (74% identical), mouse Degs1l (73% identical), rat Degs1l1 (67% identical), and 3 more. Paralogues in human: DEGS2 (63% identical).